PARP1 (poly(ADP-ribose) polymerase 1)
Diseases named in the same sentence as PARP1 in open-access papers (continued):
Sharing a sentence is not in itself a finding about the gene and the disease.
triple-negative breast carcinoma (continued). "Moreover, it was recently demonstrated that in triple negative breast cancers, miR-181 a/b are negative regulators of ATM expression and that these two miRNAs sensitize cancer cells to poly-ADP-ribose-polymerase 1 (PARP1) treatments." (PMID 26056584, 2014). "Therefore, a combination of PARP1 inhibitors, CRISPR/Cas9 technology, and chemotherapy may be helpful in the effective treatment of triple-negative breast cancer with mBRCA1." (PMID 35715750, 2022). "In order to understand whether genes involved in NAD+ metabolism, other than PARP1, might be synthetic lethal with BRCA-gene defects, we carried out parallel siRNA screens in isogenic BRCA1-defective and BRCA1-proficient triple-negative breast cancer cell lines." (PMID 34750509, 2021).
Alzheimer disease (38 papers, 2014 to 2026). A progressive, neurodegenerative disease characterized by loss of function and death of nerve cells in several areas of the brain leading to loss of cognitive function such as memory and language. "We show that polymorphisms in the human PARP1 gene or the intake of vitamin B are associated with a decrease in the risk and severity of Alzheimer’s disease." (PMID 34172715, 2021). "Poly(ADP-ribose) (PAR) polymerase 1 (PARP1) has been implicated in DNA damage responses and neuroinflammation in Alzheimer's disease (AD), yet its role in amyloid-beta (Aβ) pathology remains unclear." (PMID 42139290, 2026). "In addition, mutations in PARP1 genes have been associated with changes in the susceptibility and severity of Alzheimer’s disease; therefore, targeting NAD+ metabolism and PARP activity may be a therapeutic option in the treatment of neurodegenerative diseases." (PMID 39766263, 2024). "Concomitant increase of Chop expression and Parp-1 cleavage has also been found in neurodegenerative diseases such as Alzheimer’s disease." (PMID 35883886, 2022). "Alzheimer’s disease (AD) is featured with cognitive impairment, amyloid β (Aβ) production, and PARP1 activation." (PMID 35806303, 2022). "Several studies have also demonstrated that PARP-1 is over-activated in brains of patients with Alzheimer’s disease." (PMID 35158955, 2022). "In the brain of patients with Alzheimer’s disease, extensive PARP-1 activation is considered an early and important event of the pathogenesis." (PMID 35455964, 2022). "Our research gave a clue to search for new agents based on AChE and PARP-1 dual-inhibited activities to treat Alzheimer's disease." (PMID 30427217, 2019). "Previously, we showed that nucleolar PARP-1 is significantly decreased in hippocampal pyramidal cells in Alzheimer's disease (AD)." (PMID 31827497, 2019). "PARP-1 enzymes are involved in a number of neurodegenerative disorders including Alzheimer’s disease and PD (Martire, Mosca & d’Erme, 2015)." (PMID 29062606, 2017). "PARP1 activation drives neuronal death elicited by fragments of peptide β-amiloid, implicating PARP1 in the pathogenesis of Alzheimer's disease." (PMID 24243533, 2014). "Other disease models in which PARP1 inhibitors have cytoprotective effects include Alzheimer's disease (AD), Huntington's disease (HD) and amyotrophic lateral sclerosis (ALS), experimental retinal detachment, as well as ischemia/reperfusion injury of the kidney or the liver." (PMID 36743979, 2023). "Furthermore, recent studies investigated the therapeutic potential of various PARP-1 suppressors for other refractory diseases such as Alzheimer’s disease (AD)." (PMID 35956876, 2022). "In mixed cultures of neurons and glial cells, β-amyloid peptide, the major neurotoxic agent in the pathophysiology of Alzheimer's disease, evokes oxidative stress followed by hyperactivation of PARP-1, depolarization of mitochondrial membrane and finally cell death." (PMID 25741230, 2015). "Interestingly, PARP-1 overactivation was also demonstrated in the brain of transgenic Alzheimer's disease mouse model." (PMID 25741230, 2015). "Based on these results, we suggest that drugs targeting PARP1, mitochondrial respiration, and ATP synthase may hold potential as chemotherapeutic agents when combined with DNA damage-inducing drugs in cardiovascular diseases, Alzheimer’s disease, and cancer." (PMID 26522181, 2015). "In this work, we combined genetic, molecular and biochemical approaches to investigate the effects of two different PARP-1 inhibitors (olaparib and MC2050) in Drosophila models of Alzheimer’s disease by exploring their neuroprotective and therapeutic potential in vivo." (PMID 35455964, 2022). "Furthermore, PARP-1 inhibition using nicotinamide or PJ34, which have now been established as weak inhibitors, in transgenic mouse models of Alzheimer’s disease ameliorates brain pathology through a reduction of β-amyloid production." (PMID 35158955, 2022).
Alzheimer disease (continued). "Studies have shown that PARP-1 hyperactivation depletes NAD+, induces an accumulation of Poly (ADP-ribose) (PAR), and triggers mitochondrial damage in Alzheimer’s disease (AD), Huntington’s disease (HD), amyotrophic lateral sclerosis (ALS), ischemic brains, and PD." (PMID 34220490, 2021).
viral infection (38 papers, 2012 to 2026). "The viral utilization of PARP1 to modify viral episomes or host genes has been implicated in helping long-term viral infection in several DNA viruses as viruses utilize PARylation to affect pro-viral changes to themselves or the host." (PMID 38392869, 2024). "For instance, PARP-1 is the dominant transcription regulator of viral infection, replication, and virulence where it has been implicated in the virus-induced inflammation via regulating the expression of cytokine production." (PMID 35655915, 2022). "However, if PARP1-mediated cell death is involved in the pathogenicity and the clinical symptoms caused by the viral infection, it could also play an important role in eliminating intracellular pathogens." (PMID 33808354, 2021). "At the same time, excessive activation of PARP1 is also closely related to apoptosis in some viral infections." (PMID 41460301, 2025). "During oxidative stress and viral infection, PARP1 gets activated, synthesizes PAR chains, and releases them into the cytoplasm." (PMID 40904702, 2025). "Nevertheless, essential epigenetic mechanisms regulated by PARP1 and are eventually relevant to virus infection are further discussed." (PMID 38392869, 2024). "PARP1 has been linked to this regulation of HCMV infection, with HCMV infection enabling increased PARylation by PARP1, possibly due to increased DNA damage during viral infection or as a promotor of viral replication." (PMID 38392869, 2024). "In peritoneal macrophages, PARP1 controls NK cell recruitment to the site of vaccinia viral infection, by promoting the production of chemokine CCL216." (PMID 38332126, 2024). "It has been shown that human PARP1 is translocated from nucleus to cytoplasm in response to viral infection." (PMID 38690366, 2024). "Recent findings surrounding responses to viral infection show PARP-1 regulates recruitment of NK cells to infected sites through NF-κB-mediated MCP-1 production." (PMID 34485381, 2021). "It is possible that PARP1 reactivates the transcription of TMPRSS2 during viral infection, however further research is needed to make any statement." (PMID 34445373, 2021). "In vaccina virus infection, PARP1 plays a role in NK cell migration to the site of infection and promotes CCL2 production." (PMID 35095818, 2021). "Hyperactivation of poly(ADP-ribose) polymerase 1, which is usually seen after viral infections, leading to NAD+ depletion and consequently endothelial cell dysfunction." (PMID 34451848, 2021). "Unfortunately, only a limited number of studies have discussed the repurposing of PARP1 inhibitors in other disease models (e.g., inflammatory or viral diseases)." (PMID 34698261, 2021). "This phenomenon is also observed during viral infections where PARP1 is cleaved and therefore activated." (PMID 33808354, 2021). "Some of the first reports of PARPs and ADP-ribosylation impacting virus infection focused on the role of PARP1 on retrovirus and HIV-1 integration and replication." (PMID 32029454, 2020). "The immunomodulatory role of PARP1 was also documented upon viral infection, where PARP1 acts as both a pro- and antiviral factor in various cell types." (PMID 32900001, 2020). "A previous study has shown a role for PARP-1 in NK cell migration to the site of viral infections." (PMID 36839682, 2023). "Our results suggest that PARP1 could act as a key molecular actuator in the regulatory network which integrates coilin activities as a stress sensor for virus infection and SA-mediated antivirus defence." (PMID 37376582, 2023). "It is possible that PARP1 reactivates the transcription of TMPRSS2 during viral infection." (PMID 35162972, 2022). "In general, studies have highlighted that PARP-1 inhibitors may be useful therapeutic targets for viral infections." (PMID 34698261, 2021). "Moreover, PARP1 is critical in viral infections, including the retroviruses, herpesviruses, influenza virus, hepatitis B virus, and chikungunya virus." (PMID 35095818, 2021).
viral infection (continued). "Additionally, PARP1 plays a key part in various viral infections, such as retrovirus, hepatitis B virus, and herpesvirus infections." (PMID 33508027, 2021). "For instance, PARP-1 controls NK cell recruitment to the site of viral infection." (PMID 32046278, 2020). "In addition to T-cell lymphopenia affecting both the CD4+ and CD8+ compartment, virus infection also revealed a redundant role of PARP-1 and PARP-2 in T-cell effector function." (PMID 28181505, 2017). "In addition to its crucial role as an oncology target, abnormal increase in the activity of PARP, especially PARP‐1, has been reported in conditions of neurodegenerative diseases, cancer, cardiovascular diseases, viral infections, and so on in preclinical studies." (PMID 39215404, 2024). "However, many reports show that PARP1 is relevant for viral infections." (PMID 34871367, 2021). "Combination of viral infection and irradiation consistently activated markers of apoptosis to high levels, with the combination of viral infection and 131I showing higher levels of PARP-1 cleavage than the combination with external beam radiation in DU145 and LNCaP." (PMID 26814609, 2016). "Since these studies also show that PARP1 enzymatic inhibitors positively regulate viral replication, the use of small molecules targeting only the PARP1 catalytic domain may be contraindicated in many patients with such viral infections." (PMID 24970148, 2012). "The results revealed that, upon viral infection, the mRNA levels of NAD+-consuming enzymes, including Sirt1-7, Parp1, Parp10, Parp12, Parp14, and CD38, were substantially upregulated." (PMID 40006932, 2025). "Upon viral infection, DNA damage triggers the translocation of nuclear poly(ADP-ribose) polymerase 1 (PARP1) to the cytoplasm, interacts with cGAS, and catalyzes PARylation at D191, thus blocking dsDNA binding." (PMID 40470467, 2025). "PARP1–3 are activated by DNA damage, whereas the mono-ARTs PARP10, PARP11 and PARP12 are upregulated during viral infection leading to translational shut-down." (PMID 36018800, 2022). "NAD+ bioavailability decreases as we age and during viral infections, in part due to upregulation of NAD+ consuming enzymes, such as poly(ADP-ribose) polymerase 1 (PARP1), which interacts with NF-kB signaling, precipitating further chronic inflammation and oxidative stress." (PMID 37535668, 2023). "Here, we discuss, based on published reports, PARP1-dependent TMPRSS2 regulation through auto-poly(ADP-ribosyl)ation, since viral infection stimulates pro-inflammatory pathway via the induction of iNOS and cytokines (IL6), increases the ROS in cells, and causes ssDNA damage." (PMID 34445373, 2021). "Therefore, to curb virus infection, both promoting type I IFN signaling to boost innate immunity and prevention of virus entry by inhibiting PARP1, ACE2 or TMPRSS2 are safe options." (PMID 34445373, 2021). "Interestingly, PARP1 plays a role in the infection of other DNA viruses, including HSV-1 and KSHV, which are also epigenetically regulated by CTCF, thus suggesting that PARP1 and CTCF interaction might be a common regulatory axis of viral infection." (PMID 37243174, 2023). "Interestingly, neither virus infection (TRV) nor MV treatment were able to modulate PARP1 gene expression, which suggests other regulatory mechanisms, likely operating on the level of activity/location of PARP1 protein, could be involved." (PMID 39273315, 2024).
Ewing sarcoma (34 papers, 2013 to 2025). A small round cell tumor that lacks morphologic, immunohistochemical, and electron microscopic evidence of neuroectodermal differentiation. "To clarify whether the anticancer activity of MPH is dependent on its PARP1 inhibition, we constructed a PARP1-deficient cell line using the transcription activator-like effector nuclease technique (TALEN) technique in Ewing sarcoma RD-ES cells." (PMID 27926532, 2017). "PARP1 inhibition has initially been proposed as a therapeutic strategy in Ewing sarcoma, subsequent to the identification of an interaction between PARP1 and the fusion transcripts that potentiated DNA damage." (PMID 39412947, 2025). "This control of PARP-1 expression allows Ewing’s sarcoma cells to resist ionizing radiation and genotoxic agents." (PMID 37686260, 2023). "The shRNA-mediated silencing of EWS-FL1 ablated the impact of inhibiting PARP-1 on Ewing sarcoma cell radiation responsivity." (PMID 37351512, 2023). "Currently there is an abundance of preclinical evidence which supports the theory that Ewing’s sarcoma gene fusions depend on PARP1 activity and that tumor cell lines harboring these fusions are extremely vulnerable to PARP blocking." (PMID 36160449, 2022). "Inhibitors of Insulin-like growth factor 1 receptor (IGF1R) and poly-(ADP-ribose) polymerase (PARP1) are also under investigation for treatment of Ewing’s sarcoma." (PMID 34683845, 2021). "PARP inhibitors are also effective in Ewing's sarcomas by blocking, on the one hand, PARP1-dependent transcriptional activation effects of ETS gene fusions such as EWS-FLI-1, and by exacerbating DNA damage on the other." (PMID 32029455, 2020). "PARP1 loss led to reduced DNA damage response and ~362-fold resistance to five PARP inhibitors (PARPis) in Ewing sarcoma cells." (PMID 31992690, 2020). "Ewing’s sarcoma cells exhibit high levels of DNA damage and similarity in phenotype to BRCA1/2 mutant breast cancer, providing a molecular basis for the high sensitivity of Ewing’s sarcoma to PARP1 inhibitors." (PMID 30684955, 2019). "Clofarabine also induced apoptosis in Ewing sarcoma cells, as assessed using annexin-V staining, activation of caspsase-3/7, and cleavage of PARP-1." (PMID 29152060, 2017). "Among STSs, increased expression of PARP1 has been reported in Ewing sarcoma and the expression of PARP1 was upregulated by EWS-FLI1 fusion protein." (PMID 27643881, 2016). "Knockdown of EWS/FLI in Ewing sarcoma cells led to a significant reduction in both PARP-1 protein expression and promoter activity." (PMID 27635231, 2016). "Combination of PARPi with temozolomide would thus be predicted to enhance the level of PARP1 trapping in Ewing’s sarcoma tumors to achieve greater clinical efficacy." (PMID 26505995, 2015). "EWSR1 rearrangements in Ewing's sarcoma have recently been shown to confer sensitivity to PARP-1 inhibition." (PMID 23637631, 2013). "Furthermore, the depletion of Fli1 in Ewing’s sarcoma cells leads to the disappearance of PARP-1 expression." (PMID 37686260, 2023). "Combining 4 Gy radiation with PARP-1 inhibition reduced the growth of SK-N-MC xenograft tumors, demonstrating that inhibiting PARP-1 in Ewing sarcomas can synergistically prolong and exacerbate radiation-induced DNA damage-promoting apoptotic death in an EWS-FLI1-dependent manner." (PMID 37351512, 2023). "Indeed, in Ewing’s sarcoma cells, analysis of the PARP1 promoter showed its up-regulation in response to DNA damage, and this is carried out by ETS transcription factors, Ets-1 and Fli1." (PMID 37686260, 2023). "Brenner and members found that EWS-FLI1 genes in Ewing’s sarcoma could maintain PARP1 expression via a positive feedback loop." (PMID 28991194, 2017). "Based on this finding, they examined the role of PARP1 and PARPi in Ewing’s sarcoma." (PMID 27336789, 2016). "Notably, Ewing sarcoma cell lines are also known to be sensitive to PARP-1 inhibitors and combinations of PARP-1 inhibitors with DNA-damaging agents." (PMID 27557498, 2016).
Ewing sarcoma (continued). "Recently, the use of PARP1 inhibitors alone or in combination with other chemotherapeutic agents showed anti-tumor activity in rhabdomyosarcoma, malignant peripheral nerve sheath tumors and Ewing sarcoma cells." (PMID 27643881, 2016). "Analysis of the Broad Institute Cell Line Encyclopedia46 indicates that Ewing sarcoma is the fifth highest PARP-1-expressing malignancy and that expression is significantly higher than that of other solid bone sarcomas such as osteosarcoma (P = 0.0400) and chondrosarcoma (P = 0.0176)." (PMID 27635231, 2016). "Thus, Ewing’s sarcoma was significantly sensitive to PARP1 inhibitors." (PMID 28991194, 2017). "In addition, mutations in PARP-1 and PARP-2 are seldom observed in Ewing sarcoma." (PMID 27635231, 2016). "Our study suggests that PARP1 inhibition should be evaluated in combination with the standard-of-care multi-chemotherapy regimen to assess its ability to improve treatment outcomes in Ewing’s sarcoma, with a view to at least delay the onset of recurrent disease." (PMID 26505995, 2015). "In Ewing sarcoma cell lines, a direct interaction between the EWSR1::FLI1 fusion protein and PARP1 was described." (PMID 40134582, 2025). "In Ewing sarcoma, an EWS-FLI1 fusion gene induced PARP1 expression and the fusion gene also induced DNA damage, which was potentiated by a PARP1 inhibitor." (PMID 27643881, 2016). "The DNA damage response protein, poly(ADP-ribose) polymerase 1 (PARP1), was identified as a potential target in Ewing sarcoma following demonstration that PARP1 is a transcriptional coregulator of EWS-FLI1 and that the translocation is a genetic determinant of PARP sensitivity in cellular models." (PMID 38775200, 2024). "PARP-1 function in DT may be promising, as PARP-1 inhibitors have been used as chemo/radiosensitizers in Ewing sarcoma." (PMID 37601698, 2023). "We confirmed PARP1 expression in PSaRC318, A673, and CHLA10 Ewing sarcoma cells." (PMID 36187937, 2022). "Interestingly, PARP1 has been repeatedly shown to be a target gene of ETS1 transcriptional activity in Ewing sarcoma." (PMID 33333852, 2020). "In addition to catalytic inhibition, PARP inhibitors exert their cytotoxicity by tightly trapping PARP-1 and PARP-2 to DNA at sites of single-strand breaks, andin vitro Ewing sarcoma inhibitor sensitivity correlates with PARP trapping potential." (PMID 27635231, 2016). "Ewing sarcoma intratumoral blood vessels expressed Y1R; Ewing sarcoma cells express NPY, Y1R, and Y5R, and the peptide via both receptors promoted the death of tumor cells, which was mediated by poly(ADP-ribose polymerase) (PARP-1) and apoptosis-inducing factor (AIF)." (PMID 37373115, 2023). "Moreover, transcriptional regulation of FoxO1 by PARP1 is not just limited to Ewing sarcoma cells; similar changes were observed in CAPAN1 cells." (PMID 31992690, 2020). "We assessed PARP1/2 (rucaparib) and DNA-PK (NU7441) inhibitors in Ewing sarcoma (ES) cell lines by performing growth inhibition and clonogenic assays." (PMID 29371919, 2017). "Among the tested BSTS histotypes, Ewing’s sarcoma cells were the most sensitive to the combination, a result that might be explained by the known exquisite sensitivity of the pathognomonic fusion protein EWS/FLI1-expressing cells to both trabectedin and PARP1 inhibition." (PMID 28454547, 2017).